IL2 (interleukin 2)
Diseases named in the same sentence as IL2 in open-access papers (continued):
Sharing a sentence is not in itself a finding about the gene and the disease.
psoriasis (continued). "Anti IL-2/IL-2 complex therapy effectively ameliorated the clinical manifestations of psoriasis, with no apparent side effects, providing a new strategy for treating psoriasis." (PMID 41254515, 2025). "Furthermore, the relative number of CD4+Foxp3+CD25+ cells showed increases in psoriasis mice treated with anti-IL-2/IL-2 complex as compared to other groups." (PMID 41254515, 2025). "A meta-analysis, including 57 studies conducted on 2838 psoriasis patients, concluded that increased serum levels of IL-2, IL-17, IL-18, and IFN-γ significantly correlated with psoriasis, highlighting their potential role as biomarkers for monitoring disease activity." (PMID 40699767, 2025). "Results indicate that elevated levels of circulating inflammatory cytokines IL-2, IL-17, IL-18, and IFN-γ are related to enhanced risk of psoriasis and may help to predict clinical outcomes in individuals with psoriasis." (PMID 37883350, 2023). "The results of this meta-analysis suggest that circulating levels of IL-2, IL-17, IL-18, and IFN-γ may serve as biomarkers of psoriasis risk." (PMID 37883350, 2023). "Various cytokines and adhesion molecules, including interleukin (IL)-1, IL-2, IL-6, IL-8, IL-12, IL-18, TNF-α, and nerve growth factor, are abnormally expressed in the lesions of psoriasis patients, suggesting that psoriasis is associated with the release of NF-κB-regulated inflammatory cytokines." (PMID 36835162, 2023). "Studies found that cytokines secreted by T cells associated with psoriasis are almost Th1 related cytokines (IL-2, IFN-γ, and TNF-a), but not Th2 type cytokines (IL-4 and IL-10)." (PMID 37942312, 2023). "However, the lesion skin of psoriasis patients exhibits epidermal dysfunction and diminished expression of filaggrin, likely influenced by cytokines such as IL-2." (PMID 37795084, 2023). "Despite early positive results, α-IL-2 agents have fallen out of favor for treatment of psoriasis due to relatively high toxicity and intermediate treatment response compared to other biologics for psoriasis." (PMID 36675037, 2023). "Early findings from case reports showed promising results of IL-2 agents for psoriasis." (PMID 36675037, 2023). "Nicotine is known to induce cytokine production, specifically increasing levels of tumor necrosis factor (TNF), interleukin-12 (IL-12), interleukin-2 (IL-2), and granulocyte-monocyte colony-stimulating factor, all of which are considered central to the pathophysiology of psoriasis." (PMID 35847770, 2022). "IL-2 and IL-1β, together with theconcentrations of leucine, alanine, glutamine, glutamate, and choline,can be considered promising biomarkers for the early diagnosis andcorrect prognosis of psoriasis patients." (PMID 33164516, 2021). "Similarly, another recent study investigated the effect of low-calorie ketogenic diet in 30 patients with psoriasis by evaluating clinical symptoms, biochemical markers, metabolomic profile and inflammatory markers (IL-2, IL-4, IL-1β, TNF-α, IFN-γ)." (PMID 33499118, 2021). "The present meta-analysis found that TNF-α, IFN-γ, sE-selectin, IL-2, IL-6, IL-8, IL-18, IL-22, fibrinogen and C3 were elevated in serum of patients with psoriasis, indicating that serum levels of these cytokines may correlate to their levels in tissue." (PMID 29416693, 2018). "IL-2 signaling is essential for the development, function and homeostasis of regulatory T cells, and increased levels of this cytokine have been shown in skin diseases, such as psoriasis." (PMID 27669234, 2016). "Similarly, the pathogenesis of psoriasis involves key Th1 and Th17 inducing cytokines like TNFα, IL-1β, IL-2, IL-6, IL-10, IL-12p70, IL-23, CCL2, 3, 4, 5, 20, CXCL1, 8, 9 and 10, many of which are induced by cocktail treated DCs." (PMID 20663192, 2010). "Although these anti-CD25 agents suggest efficacy as a potential therapy for psoriasis, combining treatment with IL-2 inhibitors may yield even better clinical outcomes." (PMID 20040934, 2008).
psoriasis (continued). "Conversely, BT patients showed a distinct cytokine profile characterized by significantly reduced levels of IFN-γ, IL-2, IL-17F, and IL-22 compared to UT patients, highlighting the potent immune-modulating effects of biological treatments in attenuating pro-inflammatory pathways in psoriasis." (PMID 39769151, 2024). "Th1 cells are the main source of pro-inflammatory cytokines such as TNF-α, IFN-γ, and IL-2 in the peripheral blood and lesion areas of psoriasis patients, while Th2 cells mainly secrete the cytokine IL-4, which significantly increases in patients with erythrodermic psoriasis." (PMID 38255845, 2024). "Thus, low-dose IL-2 provides a new strategy for the treatment of psoriasis." (PMID 37596509, 2023). "In conclusion, serum levels of TNF-α, IFN-γ, IL-2, IL-6, IL-8, IL-18, IL-22, chemerin, lipocalin-2, resistin, sE-selectin, fibrinogen and C3 were significantly elevated and serum level of adiponectin was significantly decreased in psoriasis patients compared to healthy individuals." (PMID 29416693, 2018). "Whole blood from healthy volunteers or psoriasis patients was pretreated in vitro with JNJ-77242113, then stimulated with IL-23 in the presence of IL-2 and IL-18." (PMID 39080319, 2024). "Here, we show that xenografting of lesional skin from psoriasis patients onto human IL-2 NOG mice results in increased numbers of human CD3+ cells in the grafts, axillary lymph nodes and blood from human IL-2 NOG mice compared to C.B-17 scid and NOG mice." (PMID 36649237, 2023). "Increased serum concentrations of the circulating inflammatory cytokines IL-2, IL-17, IL-18 and IFN-γ were significantly correlated with psoriasis." (PMID 37883350, 2023). "In psoriasis, Tc1 cells release IFN-γ, IL-2, and TNF-α, playing different roles during the development of psoriasis." (PMID 37942312, 2023). "Th1 cells increase the production of IL-2, TNF-α, and IFN-γ, participating in the development of psoriasis." (PMID 35126161, 2022). "Elevated levels of TNF-α, IL-2, and INF-γ, and reduced levels of IL-10 in psoriasis compared to the control group." (PMID 35454992, 2022). "Nicotine in tobacco smoke was the major alkaloid of cigarettes that activated the interleukin-1β (IL-1β), IL-2, IL-12, and tumor necrosis factor (TNF), which played a central role in psoriasis pathogenesis." (PMID 35646971, 2022). "Four-weeks of VLCKD resulted in 10% weight loss, 50% reduction in PASI score, improvement of biochemical markers related to psoriasis (folic acid, vitamin B12, cortisol, bilirubin, calcium, LDL, cholesterol) and decreased IL-1β and IL-2 levels." (PMID 33499118, 2021). "In a psoriasis mouse model, curcumin significantly inhibited secretion of inflammatory factors including interleukin (IL)-17, IL-22, IFN-γ, IL-2, IL-8 and TNF-α in T cells by 30%–60% in vitro." (PMID 32143311, 2020). "By analogy to Sjögren’s syndrome, the observed increases in TNF-α, IL-2, and INF-γ concentrations allow us to assume that salivary glands of patients with psoriasis are infested with autoreactive Th1 lymphocytes." (PMID 32164227, 2020). "Increased levels of TNF-α, IL-2, and INF-γ, as well as decreased content of IL-10 in NWS and SWS of psoriasis patients compared to the controls indicated an imbalance between Th1 and Th2 cells in the salivary glands." (PMID 32164227, 2020). "Clinical studies have confirmed the safety of low‐dose IL‐2 in therapying various autoimmune and inflammatory chronic diseases (including RA, ankylosing spondylitis, SLE, and psoriasis)." (PMID 33098626, 2020). "The concentration of TNF-α (↑19.77%, p = 0.0002) and IL-2 (↑15.54%, p = 0.03) in SWS of patients with hyposalivation was considerably higher than in psoriasis patients with normal saliva secretion." (PMID 32164227, 2020). "The expressions of crucial inflammatory mediators (including IL-1β, IL-2, IL-6, IL-10, IL-17, IL-22, IL-23, IFN-γ, TNF-α) in skin tissues were measured by ELISA due to the import role of inflammatory cytokines in psoriasis." (PMID 31181689, 2019).
psoriasis (continued). "At the skin lesions of psoriasis, the accumulation of cytokines, such as IL-2 and TNF-alpha, will promote the development of psoriasis." (PMID 29588654, 2018). "Serum levels of IL-1RA, IL-2, IL-23, IFN-γ, and LL-37 were elevated in patients with psoriasis compared with the controls." (PMID 25197165, 2014). "In psoriasis, IFN-gamma, the prototype Th-1 cytokine, interplays with IL-2, TNF-alpha, IL-17, and IL-22 to contribute to inflammation and altered differentiation." (PMID 23468834, 2013). "The proportion of CD8+CCR4+ T cells is increased in the peripheral blood of patients with psoriasis and palmoplantar pustulosis, and CD8+CCR4+ T cells effectively produce IL-4, IFN-γ, IL-2, and TNF-α." (PMID 21483764, 2011). "Another recent meta-analysis, which summarized data from several small studies showed that among numerous inflammatory markers, elevated serum concentrations of the inflammatory cytokines IL-2, IL-17, IL-18, and IFN-γ are present in untreated psoriasis patients." (PMID 39775226, 2025). "CTLs secrete IL-2, IFN-γ, TNF-α, IL-17, and IL-22, which contribute to psoriasis development." (PMID 40906403, 2025). "Serum levels of IL-17, IL-2, IL-18, and IFN-γ were substantially correlated with psoriasis." (PMID 39459618, 2024). "Overall, our meta-analysis suggests that circulating inflammatory cytokine IL-2, IL-17, IL-18 and IFN-γ levels may be potent biomarkers of psoriasis in patients." (PMID 37883350, 2023). "Psoriasis is characterized by the Th1 and Th17 polarization of the adaptive immune response, with keratinocytes being activated mainly by the mediators such as interferon gamma (IFN-γ), TNFa, IL-2, and IL-17." (PMID 36830855, 2023). "Furthermore, curcumin intervention in T cells obtained from a mouse model of psoriasis showed that 10 μM curcumin concentration significantly blocked the secretion of IL-17, IL-22, IFN-γ, IL-2, IL-8 and TNF-α." (PMID 35979355, 2022). "TNF-α concentration (↑69.77%, p ≤ 0.0001; ↑103.32%, p ≤ 0.0001, respectively) and IL-2 (↑45.10%, p ≤ 0.0001; ↑67.65%, p ≤ 0.0001, respectively) in SWS of patients with psoriasis with normal and decreased saliva secretion was significantly higher than in the control group." (PMID 32164227, 2020). "In the presented study, we evaluated the concentrations of TNF-α, IL-2, INF-γ, IL-10, and selected nitrosative stress parameters (NO, peroxynitrite, S-nitrosothiols, and nitrotyrosine) in NWS and SWS, as well as the plasma of psoriasis patients." (PMID 32164227, 2020). "The concentration of IL-2 (↑10.91%, p = 0.007; ↑33.64%, p < 0.0001, respectively) and INF- γ (↑33.11%, p ≤ 0.0001; ↑57.34%, p ≤ 0.0001, respectively) in NWS of psoriasis patients with normal and decreased saliva secretion was significantly higher than in the control group." (PMID 32164227, 2020). "Moreover, concentrations of IL-2 (↑20.50%, p ≤ 0.0001) and INF-γ (↑18.21%, p = 0.005) in NWS of patients with hyposalivation were considerably higher than in psoriasis patients with normal saliva secretion." (PMID 32164227, 2020). "The levels of pro-inflammatory cytokine IL-2 was increased above normal in mononuclear cells of both forms of psoriasis, while anti-inflammatory IL-10 levels were not changed in psoriatic patients." (PMID 31480263, 2019). "We also assessed functionality of the T cells by evaluating the secretion of several inflammatory cytokines (IL-17A, IFN-gamma, IL-2, IL-33, TNF-alpha, IL-21, IL-22, and IL-27), from cell-sorted purified CD4+ and CD8+ T cells isolated from lesional and unaffected skin biopsies of psoriasis patients." (PMID 23468834, 2013). "Of these, IL-2 [SMD = 1.29 (95% CI: 0.61–1.97; P <0.001)], IL-17 [SMD = 0.71 (95% CI: 0.12–1.30; P = 0.018)], IL-18 [SMD = 1.27 (95% CI: 0.64–1.90; P <0.001)], and IFN-γ [SMD = 1.90 (95% CI: 1.27–2.52; P <0.001)] levels had significant correlations with psoriasis." (PMID 37883350, 2023).
psoriasis (continued). "Human Fc-conjugated IL-2 molecules lose in vivo exposure as early as after the first dose, potentially due to anti-drug antibody (ADA) response; thus, we opted to evaluate the impact of IL-2 with a single dose in a short-term psoriasis model induced by application of the imiquimod (IMQ) cream." (PMID 37809101, 2023). "Therefore, it could be hypothesized that activated human B-cells residing in the psoriasis skin proliferated and increased their IgG production after engraftment onto hIL-2 NOG mice possibly due to stimulation by human IL-2." (PMID 36649237, 2023). "Similarly, plasma concentration of IL-2 and INF-γ in psoriasis patients with normal secretion (↑19.68%, p = 0.002; ↑28.51%, p = 0.0006, respectively) and hyposalivation (↑29.70%, p ≤ 0.0001; ↑25.29%, p = 0.003, respectively) were significantly higher vs. control." (PMID 32164227, 2020). "Psoriasis is marked by the Th-1 and Th-17 polarization of the adaptive immune response, later followed by the increase in expression of inflammatory mediators like interferon gamma (IFN-γ), tumor necrosis factor alpha (TNF α), interleukin-2 (IL-2), and interleukin-17 (IL-17)." (PMID 33262910, 2020). "According to a cross-sectional study, psoriasis patients had increased proinflammatory macrophage type 1 (IL-1, IL-6, TNF-α), Th1 (IL-2, IL-12, IFN-γ), Th17 (IL-6, IL-17) but also anti-inflammatory Th2/T regulatory (Treg) (IL-4, IL-10) profiles which may be correlated to the severity of psoriasis." (PMID 31649677, 2019). "Interestingly the cytokine profile in the skin of patients with chronic urticaria mimics that found in patients with psoriasis, psoriatic arthritis, and rheumatoid arthritis with increased expression of TNF-alpha and IL-10 and decreased expression of IL-2 and interferon gamma." (PMID 24167521, 2013). "Indeed, we identified a major cluster of correlation comprising Ac, Asn and Gly showing positive (Ac) and negative correlation (Asn and Gly) with key cytokine of the psoriasis pathology, such as IL-17, IFN-γ, IL-2, as well as with IL-7 and FGF." (PMID 34006909, 2021).
Immunodeficiency (98 papers, 2005 to 2025). Failure of the immune system to protect the body adequately from infection, due to the absence or insufficiency of some component process or substance. "IL-2 is a crucial factor for the expansion of Treg cells, and epigenetic silencing of the IL-2 gene in T cells leads to decreased production of IL-2, contributing to reduced Tregs and a secondary immune deficiency." (PMID 39450112, 2024). "The levels of lysozyme, interleukin (IL)-2, IL-10, and IgA in blood serum at this age were minimal; starting from 28 days of age, there is a specific humoral immune deficiency, which is compensated by strengthening of cellular defense factors." (PMID 38911092, 2024). "Obesity is associated with immune dysfunction including an impaired T-cell function characterized by a lower IL-2 (proliferation marker) production after stimulation." (PMID 35187037, 2022). "Flavonoids have reported to cause increase in the helper T cells, interleukin 2 (IL-2), interferon and macrophages; hence they are useful in several diseases of immune dysfunction." (PMID 25283179, 2014). "Since IL-2 is a multifunctional cytokine, it is plausible that its deficiency disturbs proliferation and differentiation of effector cells, resulting in immune dysfunction." (PMID 25329064, 2014). "They significantly increase the activity of helper T-cells, cytokines, interleukin 2, interferon and macrophages and are thereby useful in the treatment of various diseases caused by immune dysfunction." (PMID 24250577, 2013). "Understanding of this interaction can have therapeutic potential for the design of new immunomodulatory strategies, especially in chronic disease or immune deficiency patients, for whom the homeostasis between IL-2 and IL-7 might be compromised." (PMID 41305439, 2025). "The findings of this study provide preliminary insights into immune dysfunction in the early phase of psychosis and suggest that certain cytokines, particularly IL-2 and IL-1β, may have potential diagnostic relevance." (PMID 41008291, 2025). "Previous studies have explained that T lymphocytes were damaged in the thymus and spleen causing a decreased level of interleukin (IL)-2 secretion resulting in a major immune dysfunction with alteration in the differentiation of T lymphocytes into T-helper cells and T-cytotoxic cells." (PMID 39438969, 2024). "A crucial finding scrutinizing the initial view on IL-2 was that, instead of the expected immune deficiency, mice genetically deficient for IL-2 or IL-2 receptor components developed generalized and fatal autoimmune syndromes due to an uncontrolled hyperactivity of T and B cells." (PMID 33868284, 2021). "The aging process decreases the production of IL-2 and causes immune dysfunction." (PMID 29344411, 2017). "Similar in structure to interleukin 2, an important T-cell growth factor, leptin modifies proinflammatory immune responses and may provide a key link between nutritional deficiency and immune dysfunction." (PMID 18489748, 2008). "Furthermore, because IL-2 is known to regulate the balance of the immune system, the let-7i/IL-2 pathway could be responsible for other immune deficiencies seen after HIV-1 infection (e.g., T-cell functional unresponsiveness)." (PMID 35164678, 2022). "Anti-IL-2/IL-2 complex has been proven to improve several immune disorders in mice owing to the extensive expansion and activation of Treg in vivo." (PMID 41254515, 2025). "We think that perhaps Ld IL-2 can also balance the immune disorders of D2T RA, particularly the RA subtype." (PMID 39981233, 2025). "Ld IL-2, due to its powerful ability to stimulate Treg cells, can largely balance the immune disorder in RA patients." (PMID 39981233, 2025). "In previous studies, CCL-28, FGF-19 and IL-2 were mostly investigated in immune disorders and tumor treatment 51-54, and neurturin was mainly discussed in muscular, neurodegenerative and psychiatric disorders 55,56." (PMID 40225870, 2025).